EGFR (epidermal growth factor receptor)
Diseases named in the same sentence as EGFR in open-access papers (continued):
Sharing a sentence is not in itself a finding about the gene and the disease.
lung adenocarcinoma (continued). "For example, in lung adenocarcinoma, ~30% of tumors carry a mutation in the KRAS gene and ~15% carry a mutation in EGFR, but these mutations are mutually exclusive." (PMID 29854275, 2018). "We therefore conducted a retrospective review of Asian patients with exon 19 EGFR-mutant lung adenocarcinoma and brain metastases." (PMID 30458751, 2018). "The comparison was carried out by selecting an EGFR-mutant lung adenocarcinoma patient with known drug-resistance mechanisms to EGFR inhibitors via MET amplifications from the TCGA cohort (NSCLC, TCGA-38-4629)." (PMID 29848362, 2018). "This study suggests that high expression levels of PHLPP1 predict a better survival from target therapy and a longer time of acquired resistance to EGFR TKIs in patients with lung adenocarcinoma." (PMID 28938613, 2017). "Concerning human populations, about 15% of Caucasian and 40–50% of Asian patients with lung adenocarcinoma present alterations in the EGFR gene." (PMID 28545225, 2017). "In lung adenocarcinoma where EGFR is overexpressed, low levels of Deptor are observed with a consequent enhanced mTOR kinase activity." (PMID 28086984, 2017). "The detection of EGFR genotype is also important to optimize treatment in patients with lung adenocarcinoma." (PMID 28877268, 2017). "We suggest that through bypassing the driving oncogene EGFR itself, the YAP1 pathway can act as a promising alternative therapeutic target for lung adenocarcinoma patients with EGFR-dependency including those with EGFR T790M gatekeeper mutation." (PMID 29163769, 2017). "in terms of long-term survival in lung adenocarcinoma (adenoCA; wild-type [WT] epidermal growth factor receptor [EGFR]) and squamous cell carcinoma (squCA) settings." (PMID 27835914, 2017). "We observed 28.4% EGFR mutations and 13% KRAS mutations in lung adenocarcinoma patients, consistent with our previous report." (PMID 27998968, 2017). "Our data provide evidence that YAP1 can act as a promising therapeutic target for EGFR-depenedent lung adenocarcinoma." (PMID 29163769, 2017). "Afatinib (GilotrifTM) is widely used to treat patients with mutant activating epidermal growth factor receptor- (EGFR-) dependent lung adenocarcinoma; however, it has various adverse side effects." (PMID 28948057, 2017). "To validate the activation of IGF1R/NF-κB p65 signaling in gefitinib-resistant mouse lung adenocarcinoma, we used genetically engineered mice harboring a doxycycline-inducible human EGFR exon 19 deletion transgene (hEGFR Del19)." (PMID 29190911, 2017). "All Patients were diagnosed pathologically with advanced lung adenocarcinoma (IV stage) and EGFR wild-type." (PMID 29029508, 2017). "Patients with elevated serum CEA levels responded more positively to EGFR-TKIs, and lung adenocarcinoma patients with high serological CEA levels exhibited a higher rate of EGFR mutations." (PMID 28705152, 2017). "In this study, we found that a portion of lung adenocarcinoma patients with concomitant EGFR and ALK alterations." (PMID 28887531, 2017). "As for the common driver events (i.e. EGFR mutation and ALK rearrangement) the presence of sub-clonality in lung adenocarcinoma is under debate." (PMID 28501852, 2017). "By reducing YAP1 activity through different mechamnisms, EGFR-dependent lung adenocarcinoma cells were effectively killed." (PMID 29163769, 2017). "The striking role of sortilin in EGFR trafficking should be investigated in the context of other TKRs that are involved in initiation and progression of lung adenocarcinoma." (PMID 29084952, 2017). "The EGFR-TKIs gefitinib and erlotinib have been successfully utilized as first-line therapies for lung adenocarcinoma patients." (PMID 29228636, 2017). "This study provides evidence that YAP1 can act as a promising alternative therapeutic target in patients with EGFR-mutant lung adenocarcinoma, including those with EGFR T790M." (PMID 29163769, 2017).
lung adenocarcinoma (continued). "Correlations between EGFR or KRAS mutation status and clinicopathological factors including SUVmax were statistically analyzed in 734 surgically resected lung adenocarcinoma patients." (PMID 28422979, 2017). "Lung adenocarcinoma with epidermal growth factor receptor (EGFR) mutation has strong invasion ability, but the effects of this mutation on local invasion in early lung adenocarcinoma have been rarely studied." (PMID 28253871, 2017). "In a clinical study, 4 out of 9 patients with EGFR-mutant lung adenocarcinoma exhibited changed EMT status pre-and post-gefitinib treatments." (PMID 27757846, 2017). "In this study, we have addressed the importance of YAP1 in lung adenocarcinomas by identifying YAP1 as an important EGFR downstream mediator regulating cell growth." (PMID 29163769, 2017). "The aim of our study was to investigate the association between PHLPP expression and its effect on target-based therapies and acquired resistance to EGFR-TKI in lung adenocarcinoma." (PMID 28938613, 2017). "EGFR tyrosine kinase inhibitors (TKIs) that block EGFR activity are effective therapeutics for EGFR-mutant lung adenocarcinoma patients, but TKI-resistance inevitably occurs." (PMID 29163769, 2017). "For example, in lung adenocarcinomas, gene-expression profiles from tumors with somatic aberrations in EGFR or MET were negatively correlated with each other, in line with prior knowledge that MET amplification causes resistance to EGFR inhibition." (PMID 29322935, 2017). "Shp2 inhibition suppresses EGFR mutant-induced lung adenocarcinoma by attenuating ERK1/2 and Src activation." (PMID 28085101, 2017). "This study investigated the roles of YAP1 in lung adenocarcinoma by exploring its regulation and functions mediated by EGFR signaling." (PMID 29163769, 2017). "Our results further showed that downregulation of MAP4K4 prevented ERK reactivation in EGFR inhibitor erlotinib‐treated lung adenocarcinoma cells." (PMID 28306189, 2017). "EGFR and KRAS mutations were detected in 334 (46%) and 83 (11%) of the 734 lung adenocarcinomas, respectively." (PMID 28422979, 2017). "Dasatinib, verteporfin and fluvasatin, all the three YAP1 inhibitors targeting via different mechanisms effectively reduced viability in EGFR-dependent lung adenocarcinoma cells." (PMID 29163769, 2017). "In this study, we showed the results of apatinib as second-line to fourth-line treatment in EGFR wild-type advanced lung adenocarcinoma patients." (PMID 29029508, 2017). "In spite of an initial good response to epidermal growth factor receptor tyrosine kinase inhibitors (EGFR TKIs) in lung adenocarcinoma patients, resistance to treatment eventually occurs." (PMID 28938613, 2017). "Both erlotinib and gefitinib, the two first‐generation EGFR‐TKIs, exhibit significant clinical responses for patients with lung adenocarcinoma." (PMID 28639751, 2017). "For the first time, we evaluated the feasibility of CastPCR detecting EGFR and BRAF mutations in plasma cfDNA of a cohort lung adenocarcinoma patients." (PMID 28572536, 2017). "EGFR mutation in CSF was also detected in a case with suspected leptomeningeal metastasis from EGFR mutant lung adenocarcinoma, which indicates the characterization of brain tumor genomic aberrations through CSF DNA analysis is possible." (PMID 28978187, 2017). "Deptor has been found to play an important role in EGFR (Epidermal Growth Factor Receptor)-induced tumor progression of lung adenocarcinoma and its expression is significantly reduced in patients with this type of pathology." (PMID 28086984, 2017). "We report the case of a 50-year-old male patient with stage IV exon 19-del-EGFR mutant lung adenocarcinoma who progressed on second-generation TKI therapy with manifestation of symptomatic simultaneous diffuse brain and LM." (PMID 28540256, 2017).
lung adenocarcinoma (continued). "We exemplified the applicability of the model using EGFR-gefitinib treatment for Lung Adenocarcinoma (LUAD) and Lung Squamous Cell Cancer (LSCC) and the ERK2-VTX11e treatment for melanoma and colorectal cancer." (PMID 28436422, 2017). "For example, in lung adenocarcinoma, EGFR testing for mutations and ALK rearrangements allows for precision therapy with targeted kinase inhibitors, such as gefitinib for EGFR and Crizotinib for ALK fusion." (PMID 29068423, 2017). "Motivated by the results of our treatment strategy algorithm, we tested drug scheduling strategies on select tumor subpopulations in an in vitro model of EGFR mutant lung adenocarcinoma." (PMID 28287179, 2017). "Herein, we investigated the autophagy induction as well as its influence on anti-lung adenocarcinoma activity of afatinib in two activating EGFR-mutants H1975 and H1650 cells." (PMID 28676644, 2017). "The important roles of YAP1/YES in EGFR-mutant lung adenocarcinoma cells make it a potential therapeutic target for EGFR-dependent cells." (PMID 29163769, 2017). "Our study aimed to investigate the association between PH domain leucine-rich-repeats protein phosphatase (PHLPP) expression levels and the acquired resistance to EGFR TKIs in lung adenocarcinoma." (PMID 28938613, 2017). "EGFR is mainly stimulated through protein overexpression in colorectal adenocarcinoma, whereas in adenocarcinoma of the lung it is mainly activated through hyper-activating point mutations occurring in its tyrosine kinase domain." (PMID 29088281, 2017). "We excluded wild-type EGFR and T790M lung adenocarcinoma patients who were resistant to 1st-generation EGFR-TKIs such as Gefitinib and Erlotinib." (PMID 29050327, 2017). "The somatic mutations in epidermal growth factor receptor (EGFR) and v-Ki-ras2 Kirsten rat sarcoma viral oncogene homolog (KRAS) are the most frequently found in lung adenocarcinomas." (PMID 28422979, 2017). "Similar findings were observed in EGFR mutant lung adenocarcinoma preclinical models and individuals with BRAF V600E lung adenocarcinoma." (PMID 29152593, 2017). "Molecularly targeted therapies improve outcome for lung adenocarcinoma patients whose tumors harbor mutant EGFR or translocated ALK, RET or ROS1, with an encouraging response for those with mutated BRAF, MET, NTRK-1 & 2 and ERBB2." (PMID 27998968, 2017). "Currently, none of the recurrent molecular alterations, which are commonly altered in lung squamous cell carcinoma, have proven to be as predictive for response to therapy as EGFR alterations in lung adenocarcinoma." (PMID 28430586, 2017). "This patient responded to first-line treatment with erlotinib but progressed on this therapy within only four months after initial treatment, instead of the typical 9–12 month progression free survival observed in EGFR-mutant lung adenocarcinoma patients." (PMID 28287179, 2017). "Aim of this study was to investigate the role of epidermal growth factor receptor (EGFR) and anaplastic lymphoma kinase (ALK) mutational status on the risk of venous thromboembolism (VTE) in lung adenocarcinoma." (PMID 28560038, 2017). "The majority of clinical data regarding EGFR-TKIs in EGFR-mutant population are derived from lung adenocarcinoma (ADC)." (PMID 28591695, 2017). "Although patients with lung adenocarcinoma that harbors EGFR mutations benefit from EGFR-TKI therapy, Kras mutations appear to confer intrinsic resistance to EGFR-TKIs." (PMID 27329725, 2017). "For the first time, we evaluated the possibility of CastPCR detecting EGFR and BRAF mutations in cfDNA of plasma from 107 lung adenocarcinoma patients." (PMID 28572536, 2017). "We also found a small portion of lung adenocarcinoma samples have concomitant EGFR and ALK alterations by using direct sequencing." (PMID 28887531, 2017). "The joint effects of the ER and EGFR gene SNPs and HRT usage on lung adenocarcinoma risk highlight the gene-environment interaction in lung carcinogenesis." (PMID 28783064, 2017).
lung adenocarcinoma (continued). "The xenograft tumor results indicated that YAP1 was essential for tumor growth in EGFR-dependent lung adenocarcinomas in vivo." (PMID 29163769, 2017). "The discovery of EGFR mutations and ALK-rearrangements were the first molecular alterations in lung adenocarcinoma that confer sensitivity to TKIs in 2004 and 2007, heralding the initiation of the era of precision medicine for lung." (PMID 28430586, 2017). "All 6 patients in Part B had a diagnosis of lung adenocarcinoma and had received treatment with at least one first-generation EGFR TKI before enrolling in the study." (PMID 27422720, 2016). "In this study, EGFR-activating mutation status and DNA copy number abundances of EGFR, ERBB2, ERBB3, and ERBB4 were measured in 261 surgically resected lung adenocarcinomas." (PMID 26824984, 2016). "Previous studies have reported differences features according to the 2011IASLC/ATS/ERS classification between EGFR mutant (Mt) and EGFR wild-type (Wt) resected lung adenocarcinoma." (PMID 27527915, 2016). "15.4 % of EGFR wild-type lung adenocarcinoma patients showed HER-2 protein overexpression, but this was not correlated to HER-2 mutation." (PMID 27793199, 2016). "During the past decade, the advancement of EGFR-TKIs revolutionarily transformed the landscape of treatment and prognosis in advanced lung adenocarcinoma, but BM remains a therapeutically challenging issue." (PMID 27626317, 2016). "The tumor cell lines with wild type EGFR evaluated here, H441 and A549, harbor a mutated version of the KRAS proto-oncogene, a genetic feature with 30% prevalence among lung adenocarcinomas." (PMID 27248176, 2016). "In the present study, HER-2 mutation rate and protein expression level were measured in 456 patients with wild-type EGFR lung adenocarcinoma." (PMID 27793199, 2016). "Epidermal growth factor receptor (EGFR) mutations have been demonstrated to be both predictive and prognostic for patients with lung adenocarcinoma." (PMID 27486770, 2016). "The present study evaluated the mutation rate of HER-2 within the wild-type epidermal growth factor receptor (EGFR) lung adenocarcinoma population in China." (PMID 27793199, 2016). "The aim of this study was to present the EGFR, KRAS and ALK mutations in a representative cohort of patients with lung adenocarcinomas in Croatia and to correlate the mutational status with clinical data." (PMID 27655296, 2016). "For another, ginsenoside Rg3 reduces cell surface EGFR, and then attenuates EGFR signaling transduction, thus eventually inducing apoptosis in A549 lung adenocarcinoma cells." (PMID 27655708, 2016). "EGFR mutations and ALK gene fusion were thought to be mutually exclusive events in lung adenocarcinoma." (PMID 27352172, 2016). "Mutations that substitute methionine for threonine at position 790 (T790M) in the EGFR kinase domain seems to occur in approximately 50% of lung adenocarcinomas from patients with acquired resistance to the EGFR-TKIs." (PMID 26575584, 2016). "The initial surgically resected lung adenocarcinoma showed wild type PIK3CA and EGFR c.2573T > G (p.L858R) mutation." (PMID 27734950, 2016). "We also analyzed epidermal growth factor receptor (EGFR) signaling, which is a major driver of lung adenocarcinoma and has been shown to be negatively regulated by Tid1-L." (PMID 26919236, 2016). "The aim of this study was to assess the sensitivity of EGFR mutation analysis using direct sequencing, PNA-sequencing, and RNA-sequencing of MPE in lung adenocarcinoma." (PMID 27352172, 2016). "Many studies in human lung adenocarcinoma patients showed that KRAS and EGFR mutations are mutually exclusive and KRAS confers resistance to treatment with EGFR TKIs." (PMID 27458163, 2016). "We retrospectively assessed patients with EGFR-mutant stage IV lung adenocarcinoma who were treated with EGFR TKIs until disease progression." (PMID 26984681, 2016).
lung adenocarcinoma (continued). "Lung adenocarcinoma (LAC) is currently the predominant histological subtype of NSCLC with an average 5-year survival rate of 15 % despite using epidermal growth factor receptor (EGFR)-targeted therapies." (PMID 27553041, 2016). "In primary lung adenocarcinoma, there were 14 patients of mutant EGFR had mutant K-ras synchronously." (PMID 27070580, 2016). "Between February 2014 and February 2016, a total of 98 lung adenocarcinoma patients who had experienced acquired resistance to EGFR-TKI and undergone tumor rebiopsy were enrolled for analysis." (PMID 27384480, 2016). "Our case represented a breast metastasis of SCLC transformed from lung adenocarcinoma when developing acquired resistance to EGFR-TKI treatment." (PMID 27488410, 2016). "To evaluate the impact of PIK3CA mutations on EGFR TKI treatment responses, we focused on the 344 EGFR TKI-treated EGFR mutant lung adenocarcinoma patients with EGFR TKI-naïve tissue specimens." (PMID 27734950, 2016). "This is the first case report of small cell transformation and metastatic to the breast in a patient with lung adenocarcinoma following EGFR-TKI treatment." (PMID 27488410, 2016). "Further pre-clinical studies, for example in genetically-defined mouse models of EGFR T790M-driven lung adenocarcinoma, will be key for translating this preclinical finding to a potential therapeutic opportunity." (PMID 27861144, 2016). "Then, we evaluated the association of the content of mutant EGFR DNA with the treatment response to EGFR-TKI and survival in advanced lung adenocarcinoma patients with common EGFR mutations." (PMID 27368002, 2016). "We also found that EGFR copy number gain was seen in all lung adenocarcinoma patients whose tumor harbored MET exon 14 skipping in TCGA (The Cancer Genome Atlas) cohort." (PMID 27223439, 2016). "Mutant EGFR-induced lung adenocarcinoma mouse models have seen wide use as pre-clinical models for investigation of treatment strategies." (PMID 27494838, 2016). "We used doxycycline inducible bi-transgenic (tetO-EGFRmut and CCSPrtTA) lung adenocarcinoma mouse models to study the tumors’ immediate-early response to EGFR TKIs." (PMID 27494838, 2016). "Compared with the paired adjacent normal tissues, lung adenocarcinomas displayed significantly upregulated miR-26a expression, suggesting the involvement of miR-26a in the development of EGFR-TKI resistance in NSCLCs." (PMID 27285768, 2016). "The targeted drugs developed for lung adenocarcinoma such as EGFR tyrosine kinase inhibitor (EGFR-TKI) and ALK inhibitor, are largely ineffective against SqCLC." (PMID 27145277, 2016). "We enrolled a total of 98 epidermal growth factor receptor (EGFR)-mutant lung adenocarcinoma patients, who had a history of acquired resistance to EGFR-tyrosine kinase inhibitor (TKI) and available rebiopsy tumor specimens for reassessment of EGFR mutations." (PMID 27384480, 2016). "EGFR, an upstream element in signaling pathway, is a significant predictive and prognostic indicator in lung adenocarcinoma to guide the decision of targeted treatment." (PMID 27050078, 2016). "Here, the authors uncover a growth suppressive role for ZEB1 in EGFR mutant lung adenocarcinoma, thus elucidating the context dependent function of this protein." (PMID 27456471, 2016). "We have recently reported a MET-independent early onset adaptive drug escape among the parental drug-sensitive EGFR-mutant lung adenocarcinoma cells (HCC827 and PC-9 to erlotinib; H1975 to CL-387,785)." (PMID 27852038, 2016). "Sequencing of the 41 lung adenocarcinomas showed that 14 tumours had KRAS mutations, and that 7 tumours had EGFR mutations." (PMID 27456471, 2016). "Similar results were obtained and validated in another EGFR-mutant lung adenocarcinoma cell line PC-9." (PMID 27852038, 2016). "And in another study, EGFR mutations and ALK rearrangements were also found in lung adenocarcinomas with clear cell component." (PMID 27013585, 2016).